RNU7-161P (RNA, U7 small nuclear 161 pseudogene)
Gene: Small nuclear RNA gene on chromosome 5 (40,911,067 to 40,911,128, reverse strand). Ensembl gene ENSG00000253098.
Homologues: Orthologues: macaque U7 (94% identical). Paralogues in human: RNU7-13P (85% identical), RNU7-41P (85% identical), RNU7-6P (85% identical), RNU7-8P (85% identical), RNU7-11P (84% identical), RNU7-3P (84% identical), RNU7-52P (84% identical), RNU7-21P (82% identical), RNU7-22P (82% identical), RNU7-25P (82% identical), RNU7-28P (82% identical), RNU7-2P (82% identical), and 141 more.